TEX41 (testis expressed 41)
Synonyms: DKFZp686O1327; LINC00953
Gene: Long non-coding RNA gene on chromosome 2 (144,666,312 to 145,262,988, forward strand). Ensembl gene ENSG00000226674.
Diseases named in the same sentence as TEX41 in open-access papers:
TEX41 is named in the same sentence as 32 diseases in open-access papers, as found by Europe PMC text mining. Sharing a sentence is not in itself a finding about the gene and the disease. The quoted sentences say what the papers report.
head and neck squamous cell carcinoma (4 papers, 2019 to 2021). A squamous cell carcinoma that arises from any of the following anatomic sites: lip and oral cavity, nasal cavity, paranasal sinuses, pharynx, larynx, and salivary glands. "LncRNA TEX41, which has been investigated in cervical cancer and head and neck squamous cell carcinoma, was chosen as the subject of our research." (PMID 34915882, 2021). "Specifically, in head and neck squamous cell carcinoma, the expression level of TEX41 is higher than in normal tissues where, by means of inhibiting the expression of the known tumor suppressor miR-340, it induces the expression of COMMD6." (PMID 34233751, 2021). "In recent years, several studies have reported the distinct dysregulation of TEX41 in several tumors, such as cervical cancer, head and neck squamous cell carcinoma, and leukemia." (PMID 34795805, 2021). "The TEX41/miR-340/COMMD6 axis promotes the development of head and neck squamous cell carcinoma." (PMID 34915882, 2021). "Furthermore, we shed light on the underlying tumour promoting role and mechanism of COMMD6 by constructing a TEX41-miR-340-COMMD6 ceRNA network in head and neck squamous cell carcinoma and miR-218-CDX1-COMMD6 transcriptional network in cholangiocarcinoma." (PMID 31523056, 2019).
melanoma (4 papers, 2021 to 2023). A malignant, usually aggressive tumor composed of atypical, neoplastic melanocytes. "As the statistics illustrated that high TEX41 expression was associated with unfavorable prognosis of melanoma patients, the specific roles and mechanism of TEX41 in melanoma cells deserved further exploration." (PMID 34915882, 2021). "The results of qRT-PCR analysis showed that TEX41 expression was higher in melanoma cell lines (especially in A375 and SK-MEL-2 cell lines) than in HEMa-LP cell line." (PMID 34915882, 2021). "Knowing that the TEX41 had an oncogenic effect on melanoma cells, we further explored its regulatory mechanism." (PMID 34915882, 2021). "Functional experiments showed that knockdown of TEX41 inhibited melanoma cell proliferation, migration and invasion, while promoting melanoma cell apoptosis." (PMID 34915882, 2021). "Taken together, TEX41 served as an oncogene to facilitate the proliferation, migration, invasion, but hampered the apoptosis of melanoma cells." (PMID 34915882, 2021). "TEX41 knockdown hindered melanoma cell proliferation, migration and invasion while promoting cell apoptosis." (PMID 34915882, 2021). "As a miR-103a-3p sponge and C1QB modulator, TEX41 promoted proliferation, migration and invasion of melanoma cells while repressing cell apoptosis." (PMID 34915882, 2021). "Firstly, TEX41 was found to display higher expression in melanoma tissues and cells than in normal skin tissues and normal epidermal melanin cells." (PMID 34915882, 2021). "The results of colony formation assay manifested that the colony formation ability of melanoma cells was weakened when the expression level of TEX41 was decreased." (PMID 34915882, 2021). "In summary, our study mainly illustrated the role of IRF4/TEX41/miR-103a-3p/C1QB axis in melanoma cells." (PMID 34915882, 2021). "In CCK-8 assays, the proliferation ability of melanoma cells with the transfection of sh-TEX41#1/2 was significantly impaired." (PMID 34915882, 2021). "To explore the effects of TEX41 on melanoma cells, we knocked down TEX41 in A375 and SK-MEL-2 cells." (PMID 34915882, 2021). "Our study aims to explore the function of TEX41 and uncover its potential mechanism in melanoma cells." (PMID 34915882, 2021). "And high TEX41 expression was correlated with poor prognosis of melanoma patients." (PMID 34915882, 2021). "In addition, transwell assays were implemented to detect the migration and invasion ability of melanoma cells, and the results showed that the number of migrated and invaded cells was significantly reduced when the expression of TEX41 was lessened." (PMID 34915882, 2021). "To further confirm whether TEX41 exerted its functions in melanoma cells via targeting miR-103a-3p/C1QB, we conducted a series of rescue experiments." (PMID 34915882, 2021). "IRF4 up-regulated TEX41 at the transcriptional level in melanoma cells." (PMID 34915882, 2021). "Finally, TUNEL and flow cytometry assays were conducted to detect melanoma cell apoptosis, and it was found that the down-regulation of TEX41 accelerated the apoptosis of melanoma cells." (PMID 34915882, 2021). "In this study, we aimed to investigate the regulatory role of TEX41 in melanoma." (PMID 34915882, 2021). "MiR-103a-3p inhibition could recover the repressed malignant processes of melanoma cells induced by TEX41 knockdown." (PMID 34915882, 2021). "The relation between TEX41 and melanoma has been studied for the first time." (PMID 34915882, 2021). "The suppressive impact of TEX41 depletion on melanoma cell malignant behaviors could be counteracted by miR-103a-3p inhibition or C1QB overexpression." (PMID 34915882, 2021). "Furthermore, we discovered that IRF4 stimulated the transcription of TEX41 and induced the aberrant up-regulation of TEX41 in melanoma cells." (PMID 34915882, 2021). "After TEX41 knockdown, cytoplasmic TEX41 was significantly reduced in melanoma cells." (PMID 34915882, 2021).
melanoma (continued). "Rescue experiments further validated that overexpression of C1QB could counteract the effects of TEX41 depletion on the proliferation, migration, invasion and apoptosis of melanoma cells." (PMID 34915882, 2021). "Similarly, EdU assays also demonstrated that melanoma cell proliferation capacity was inhibited in response to TEX41 depletion." (PMID 34915882, 2021). "Moreover, qRT-PCR was conducted to detect the expression of TEX41 after melanoma cells were transfected with pcDNA3.1-IRF4 or sh-IRF4#1/2." (PMID 34915882, 2021). "This study aimed to explore the role and specific mechanism of TEX41 in melanoma." (PMID 34915882, 2021). "Moreover, survival analysis based on GEPIA showed that the overall survival of melanoma patients with high TEX41 expression was poorer than that of patients with low TEX41 expression." (PMID 34915882, 2021). "Testis expressed 41 (TEX41) is a relatively new lncRNA whose mechanism in melanoma remains vague." (PMID 34915882, 2021). "TEX41 may be a new potential biomarker that will be of great importance in the clinical diagnosis and treatment of melanoma." (PMID 34915882, 2021). "IRF4-activated TEX41 sequestered miR-103a-3p and modulated C1QB to promote melanoma cell malignant behaviors, for which TEX41 might be regarded as a potential therapeutic target for melanoma." (PMID 34915882, 2021). "Thus, the obtained data suggested that TEX41 played a promoting role in melanoma cells." (PMID 34915882, 2021). "All these results above manifested that miR-103a-3p could bind to TEX41 in melanoma cells." (PMID 34915882, 2021). "Therefore, we conclude that TEX41 might be a potential therapeutic target for melanoma." (PMID 34915882, 2021). "Thus we hypothesized that TEX41 might function through ceRNA network in melanoma cells." (PMID 34915882, 2021). "The expressions of TEX41 were involved in five KEGG pathways, including transcriptional misregulation in cancer, SNARE interactions in vesicular transport, mitophagy-animal, melanoma, melanogenesis, and progesterone-mediated oocyte maturation." (PMID 34795805, 2021). "TEX41 is activated by IRF4 and binds to miR-103a-3p to upregulate C1QB, thereby promoting cell proliferation, migration, and invasion while inhibiting apoptosis, suggesting that TEX41 is a potential therapeutic target for melanoma." (PMID 36034860, 2022). "Accordingly, we detected the expression of TEX41 in melanoma cell lines (A375, WM35, A2058, SK-MEL-2) and normal epidermal melanin cell line, HEMa-LP." (PMID 34915882, 2021). "In summary, TEX41 was over-expressed in SKCM tissues and melanoma cell lines." (PMID 34915882, 2021). "However, the role of TEX41 in melanoma has not been studied." (PMID 34915882, 2021).
cervical cancer (3 papers, 2021). A primary or metastatic malignant neoplasm involving the cervix. "Several studies have reported that TEX41 was dysregulated in several tumors, such as breast cancer, leukemia, and cervical cancer." (PMID 34795805, 2021). "The tumor-promoting role of TEX41 was also reported in cervical cancer." (PMID 34233751, 2021).
hepatocellular carcinoma (3 papers, 2020 to 2022). A malignant tumor that arises from hepatocytes. "TEX41 results upregulated also into portal vein tumor thrombosis which develops from hepatocellular carcinoma cells." (PMID 34233751, 2021). "TEX41, also downregulated in our study, is upregulated in portal vein tumor thrombosis (PVTT), the main route for intrahepatic metastasis in hepatocellular carcinoma." (PMID 32260415, 2020).
lymphoblastic leukemia (3 papers, 2021 to 2022). "A previous study showed that TEX41 was highly expressed in lymphoblastic leukemia and TEX41 knockdown suppressed leukemic cell growth, suggesting TEX41 acted as a tumor promoter in leukemia." (PMID 34795805, 2021).
skin cutaneous melanoma (3 papers, 2021 to 2022). "The results showed that TEX41 was expressed at a higher level in skin cutaneous melanoma (SKCM) tissues than in normal skin tissues." (PMID 34915882, 2021).
leukemia (2 papers, 2021). A malignant (clonal) hematologic disorder, involving hematopoietic stem cells and characterized by the presence of primitive or atypical myeloid or lymphoid cells in the bone marrow and the blood. "Here, we analyzed the expression of TEX41 exploiting a cohort of pediatric leukemia patients obtained from St." (PMID 34233751, 2021). "Indeed, functional experiments performed by our research group using a transient silencing approach, disclosed that TEX41 downregulation was followed by impairment of leukemia cell growth followed by cell cycle arrest in the G2-M phase." (PMID 34233751, 2021). "Our findings highlight that TEX41 is an upregulated lncRNA in the case of B-ALL and this feature makes it a novel potential biomarker for the diagnosis of this leukemia subtype in pediatric patients." (PMID 34233751, 2021).
acute myeloid leukemia (1 paper, 2021). Acute myeloid leukemia (AML) is a group of neoplasms arising from precursor cells committed to the myeloid cell-line differentiation. "We exploited the St Jude Cloud database and found that TEX41 is a lncRNA primarily expressed in the case of B-ALL (n = 79) while its expression levels are low/absent for T-cell ALL (n = 25) and acute myeloid leukemia (n = 38)." (PMID 34233751, 2021).
aortic valve stenosis (1 paper, 2020). Aortic valve stenosis (AVS) is a condition characterized by narrowing of the heart's aortic valve opening. "Indeed, from literature, TEX41 has been involved in human tumours such as squamous cell carcinoma based on a TCGA cohort and recently emerged among novel aortic valve stenosis disease loci." (PMID 32887470, 2020).
B-cell acute lymphoblastic leukemia (1 paper, 2021). A neoplasm of lymphoblasts committed to the B-cell lineage, typically composed of small to medium-sized blast cells. "Recently, fusion genes involving MEF2D have been identified in the precursor B-cell acute lymphoblastic leukemia, suggesting a potential connection between TEX41 and MEF2D." (PMID 34233751, 2021). "Our results indicate that the lncRNA TEX41 is significantly over-expressed in pediatric B-cell acute lymphoblastic leukemia in comparison with healthy subjects and its expression decreases after chemotherapy." (PMID 34233751, 2021).
coronary artery disease (1 paper, 2025). "TEX41 is an RNA gene encoding a long noncoding RNA, previously associated with inflammatory bowel disease, coronary artery disease, and various cancers." (PMID 41377660, 2025).
endometriosis (1 paper, 2021). The growth of functional endometrial tissue in anatomic sites outside the uterine body. "Whereas, in the differentially expressed gene analysis, the tumor related genes TEX41, POLQ, and FLT1 were highly expressed in the ectopic endometrial cell group of endometriosis, and the expression of tumor suppressor gene PLCD1 was down-regulated when compared with the control group." (PMID 33868805, 2021).
lung adenocarcinoma (1 paper, 2023). A carcinoma that arises from the lung and is characterized by the presence of malignant glandular epithelial cells. "They focused on investigating the functions and molecular mechanisms of TEX41, its association with Runx2, and its impact on various aspects of LUAD (lung adenocarcinoma) cell behavior, including proliferation, migration, invasion, and metastasis." (PMID 38260135, 2023). "A study was conducted to investigate the role of TEX41 in bone metastasis of lung adenocarcinoma (LUAD)." (PMID 38260135, 2023).
male pattern baldness (1 paper, 2020). "Out of 13 SNPs included in our predictive models for hair greying, 6 (FGF5 rs7680591, RUNX1 rs68088846, IRF4 rs12203592, BRINP1 rs2416699, TEX41 rs10928235, GRID1 rs2814331) were previously associated with male pattern baldness (MPB)." (PMID 32758128, 2020).
psoriasis (1 paper, 2022). An autoimmune condition characterized by red, well-delineated plaques with silvery scales that are usually on the extensor surfaces and scalp. "As with TEX41 (FC = 0.41, p = 1.4 × 10−5), ZEB2 (FC = 0.42, p = 2.8 × 10−12) is significantly downregulated in psoriasis, however there was no mQTL or other evidence for this gene." (PMID 36323703, 2022).
renal cell carcinoma (1 paper, 2025). "In renal cell carcinoma (RCC), WTAP regulates the m6A modification of long non coding RNA TEX41 to promote cancer cell proliferation and metastasis." (PMID 41256854, 2025).
Stroke (1 paper, 2022). Sudden impairment of blood flow to a part of the brain due to occlusion or rupture of an artery to the brain. "Exclusion of women younger than 50 years of age at stroke diagnosis attenuatedIVW estimates (ORIVW = 0.95, 95% CI: 0.70–1.27) and effect estimates forthe SNPs in the AMH, CDCA7 and TEX41 loci." (PMID 39076620, 2022).
tumor (8 papers, 2019 to 2024). "In this study, we aimed to explore the expression and prognostic value of an enhancer RNA TEX41 in SKCM as well as the associations between TEX41 and tumor-infiltrating immune cells (TICs)." (PMID 34795805, 2021). "Our evidence suggested that TEX41 expressions exhibited a regulatory effect on the immune activity of tumor microenvironment." (PMID 34795805, 2021). "LncRNAs KCNQ1OT1 and TUB-AS1 were lower while TEX41 was higher in tumours than those in normal tissues (P < 0.001)." (PMID 31523056, 2019). "lncRNA testis expressed 41 (TEX41) was a newly identified tumor-related enhancer RNA." (PMID 34795805, 2021). "Furthermore, we shed light on the underlying tumour promoting role and the mechanism of COMMD6 by constructing a TEX41-miR-340-COMMD6 ceRNA network in HNSC and miR-218-CDX1-COMMD6 transcriptional network in CHOL." (PMID 31523056, 2019). "TEX41 may act as a regulator in the tumor microenvironment of SKCM." (PMID 34795805, 2021). "The expression level of CCDC144NL-AS1, MNX1-AS1, TEX41, NKILA, and Z99289.2 was higher in tumor tissue." (PMID 36531020, 2022). "To investigate the role of TEX41, we first used GEPIA database to figure out the expression of TEX41 in tumor tissues and normal tissues." (PMID 34915882, 2021). "However, for the Mediate the Crosstalk Between Tumor Intermediate State and the T Exhausted State pathway, the C0 CAND2+ TCs and C3 TEX41+ TCs, G1 Phase, and Neoadjuvant had higher expression levels." (PMID 39136009, 2024).
cancer (4 papers, 2020 to 2026). A tumor composed of atypical neoplastic, often pleomorphic cells that invade other tissues. "The data revealed that TEX41 might be involved in programmed cell death, cancer metabolisms, and several pathways in tumors." (PMID 34795805, 2021). "Several non-coding RNAs (LINCs, TEX41) and non-X-linked genes that are normally expressed in testis and/or associated with cancer were also among the top 25 DEGs." (PMID 32133047, 2020). "TEX41 has also been studied in the context of cancer where it may play a role in regulating autophagy by increasing Runx2 levels, and may control cancer cell proliferation and migration by regulating miR153-3p levels." (PMID 41602168, 2026).
TEX41 also shares sentences with these, for which no sentence is quoted: aortic stenosis (2 papers); Alzheimer disease (1); asthma (1); breast carcinoma (1); cardiovascular diseases (1); cholangiocarcinoma (1); esophageal squamous cell carcinoma (1); head and neck cancer (1); inflammatory bowel disease (1); liver fibrosis (1); Obesity (1); osteosarcoma (1); squamous cell carcinoma (1).